SDC1 (syndecan 1)
Diseases named in the same sentence as SDC1 in open-access papers (continued):
Sharing a sentence is not in itself a finding about the gene and the disease.
Multiple Organ Failure (6 papers, 2019 to 2024). A progressive condition usually characterized by combined failure of several organs such as the lungs, liver, kidney, along with some clotting mechanisms, usually postinjury or postoperative. "Both cfDNA and syndecan-1 levels are reported for mortality predictions in septic subjects and are associated with adverse clinical outcomes (e.g., development of multiple organ failure, ARDS)." (PMID 36297099, 2022). "Patients with multiple organ failure showed significantly increased hyaluronan concentrations at all three time points (p = 0.007/0.006/<0.001), and the syndecan-1 levels were significantly elevated 12 h after trauma in the MOF group (p = 0.01)." (PMID 39597912, 2024). "We were especially interested in a potential correlation of the early post-ROSC concentration of the glycocalyx components hyaluronan and syndecan-1 as biomarkers for the development of postcardiac arrest syndrome and multiple organ failure." (PMID 31148947, 2019). "The patients who develop critical multiple organ failure have higher syndecan-1 levels at 12 h." (PMID 39597912, 2024). "Hyaluronan and syndecan-1 significantly correlate with multiple organ failure in our cohort." (PMID 39597912, 2024). "It is not known to date if an immediate early damage to the endothelial glycocalyx, detected by on-the-scene blood sampling and measurement of soluble components (hyaluronan and syndecan-1), precedes and predicts multiple organ failure (MOF) and survival after ROSC." (PMID 31148947, 2019). "Multivariate analysis of variances testing syndecan-1 levels, time, and development of multiple organ failure showed a highly significant correlation presenting higher syndecan-1 levels in patients suffering from multiple organ failure (MOF > 6) within 48 h after ROSC (p = 0.001)." (PMID 31148947, 2019). "Levels of syndecan-1 and hyaluronan measured immediately after ROSC predicted multiple organ failure and poor clinical outcome." (PMID 34179033, 2021). "This fits to our findings that patients with a greater extent of multiple organ failure—calculated by MOF score—consistently exhibited higher levels of hyaluronan and syndecan-1." (PMID 31148947, 2019).
oral cancer (6 papers, 2012 to 2024). "Downregulation of syndecan-1 expression has been reported in epithelial dysplasia and oral carcinoma." (PMID 32733563, 2020). "Taken together, these results suggest that reduced cellular SDC1 or increased stromal SDC1 expression can be useful prognostic factors in oral cancers." (PMID 26293675, 2015). "A selection of studies has indicated that SDC1 can suppress EMT in oral cancer cells." (PMID 38683136, 2024). "Conversely, overexpression of SDC1 was found to promote an epithelial morphology and inhibit cell proliferation in mammary epithelial cells and to suppress EMT in oral cancer cells." (PMID 34208075, 2021).
Thrombocytopenia (6 papers, 2016 to 2022). A reduction in the number of circulating thrombocytes. "Impaired vascular integrity may be the underlying mechanism linking elevated serum syndecan-1 and persistent thrombocytopenia." (PMID 34557532, 2021). "Patients with serum syndecan-1 ≥21.4 ng/mL showed delayed recovery from thrombocytopenia relative to patients with serum syndecan-1 <21.4 ng/mL." (PMID 34557532, 2021). "In our cohort, soluble EC activation biomarkers (e.g. ICAM-1, VCAM-1, E-selectin, Ang-2, CD40L, vWF-A2) and the EC damage product, Syndecan-1, are positively correlated with thrombocytopenia, lymphopenia, anaemia, and neutrophil enrichment in the peripheral blood." (PMID 34585667, 2021). "Interestingly, a tree-structured model demonstrated that PvLDH, along with VCAM-1 and Syndecan-1, is a relevant predictor attribute (high information gain) in predicting thrombocytopenia severity in our cohort." (PMID 34585667, 2021). "Indeed, patients with high serum syndecan-1 showed delayed recovery from thrombocytopenia." (PMID 34557532, 2021).
Arthritis (5 papers, 2008 to 2025). Inflammation of a joint. "Selected HSPGs, such as syndecan-1, -2 and -3 and glypican-4, could play a part in the pathophysiology of arthritis, such as the migration and retention of leukocytes and angiogenesis in the chronically inflamed synovium." (PMID 17545191, 2008). "Although the exact mechanism of the interaction between IL-34 and syndecan-1 remains elusive, it was shown that the lack of syndecan-1 impairs macrophage differentiation, ultimately attenuating murine IL-34-induced arthritis." (PMID 36530919, 2022).
Cirrhosis (5 papers, 2019 to 2023). A chronic disorder of the liver in which liver tissue becomes scarred and is partially replaced by regenerative nodules and fibrotic tissue resulting in loss of liver function. "However, etiological correlations were observed in HCC tissues: compared to normal liver areas, there was a large increase of syndecan-1 levels in cirrhosis-associated HCC and a moderate increase in non-cirrhotic HCC." (PMID 35344068, 2022). "The processes of fibrogenesis and hepatocarcinogenesis run concomitantly in cirrhosis-associated HCC; therefore, the overexpression of SDC1 may be more related to cirrhosis than to carcinogenesis, and high expression of SDC1 may ultimately counter rather than support tumor growth." (PMID 33801718, 2021). "For example, syndecan-1 was shown to increase in cirrhosis compared to normal liver tissue, without correlation with etiology." (PMID 35344068, 2022). "The authors also noticed that even syndecan-1 levels are increased both in HCC with or without previous cirrhosis, its expression being significantly higher in the former, with high levels also detected in the peritumoral cirrhotic areas." (PMID 31815014, 2019). "Syndecan-1 levels are increased in HCC both with and without previous cirrhosis; its expression is significantly greater in the former, with high levels also detected in the peritumoral cirrhotic areas." (PMID 38022112, 2023).
coronary artery disease (5 papers, 2021 to 2025). "However, it was reported that lower serum levels of SDC1 (<99.0 ng/mL) are associated with a higher prevalence of lipid-rich plaques in patients with coronary artery diseases (CADs)." (PMID 39175877, 2024). "In patients with ischemic heart disease, an increased serum level of syndecan-1 correlated with the degree of inflammation and leukocyte recruitment." (PMID 39728298, 2024). "The median syndecan-1 level in our patient group resembles mean syndecan-1 level in patients with coronary artery disease (29.5±4.6 ng/mL), in whom the level increased dramatically (98±9.8 ng/mL) after coronary artery bypass grafting." (PMID 34242246, 2021). "This is related to in vitro studies showing thinning of the endothelial glycocalyx in areas of impaired blood flow associated with atherosclerotic plaque formation and increased levels of hyaluronic acid and syndecan-1 in the plasma of patients with coronary artery disease." (PMID 39728298, 2024). "Furthermore, our results highlight the link between GCX injury and atherosclerotic disease, suggesting the potential utility of circulating SDC1 levels as a prognostic marker for coronary artery disease." (PMID 39175877, 2024). "Thus, syndecan-1 levels might be more strongly influenced by acute vascular injury or other tissue damage due to surgery, than by the coronary artery disease." (PMID 34242246, 2021).
diffuse large B-cell lymphoma (5 papers, 2006 to 2023). "Tumor biopsies of diffuse large B-cell lymphoma patients were examined for SDC1 expression and results tested positive in 30% of poor overall survival, indicating aberrant SDC1 expression correlates with poor clinical outcome." (PMID 26293675, 2015). "Multiple studies have detected SDC1 in diffuse large B-cell lymphoma." (PMID 26293675, 2015).
Disseminated intravascular coagulation (5 papers, 2015 to 2025). Disseminated intravascular coagulation is characterized by the widespread activation of coagulation, which results in the intravascular formation of fibrin and ultimately thrombotic occlusion of small and midsize vessels. "Also, increasing disseminated intravascular coagulation (DIC) score was associated with increased syndecan-1 (P <0.001) and thrombomodulin (P <0.001) and reduced protein C (P <0.001), whereas tPA and PAI-1 remained stable across DIC scores (data not shown)." (PMID 25907781, 2015).
ductal breast carcinoma (5 papers, 2010 to 2022). "The Chi-square distribution test showed a significantly stronger Sdc1 expression in the primary ductal carcinomas than in the lobular ones (Pearson χ2 test = 9.17, df = 3, P = 0.027)." (PMID 30151336, 2018). "The negative correlation between the Sdc1 expression in the tumor epithelium and the PR expression was significant in the ductal carcinomas (P = 0.014), as the positive correlation between the Sdc1 expression in the tumor stroma and the histological grade was in the lobular carcinomas (P = 0.014)." (PMID 30151336, 2018). "It is very important to emphasize that this strong Sdc1 expression in the tumor epithelium of lymph nodes might be a possible prerequisite for the further progression and metastasis of a ductal carcinoma, in the loco-regional and remote areas." (PMID 30151336, 2018). "We can assume that the somewhat weaker stromal Sdc1 expression in the lobular tumors is probably associated with a greater E-cadherin loss; that is, the tumor cells of the lobular cancers lose more Sdc1 during the EMT than the ductal carcinoma cells undergoing the EMT." (PMID 30151336, 2018). "For example, constitutive expression of the soluble HS proteogylcan, shed syndecan-1, decreased the proliferation of MCF-7 adenocarcinoma cells while exposure of T47D ductal carcinoma cells to secreted syndecan-1 stimulated their proliferation." (PMID 20975989, 2010). "A significant difference in the absence of the Sdc1 expression (null expression) between the tumor epithelium and the stroma of the ductal carcinoma metastases was found (13.3% versus 46.7%, P = 0.005)." (PMID 30151336, 2018). "The negative correlations between the Sdc1 expression in the malignant epithelium of the metastases with the age of the patients and the ER/PR expression were significant in the ductal carcinoma metastases (P = 0.043, P = 0.038, and P = 0.010)." (PMID 30151336, 2018).
experimental autoimmune encephalomyelitis (5 papers, 2014 to 2020). An autoimmune demyelinating disease of the central nervous system that is produced experimentally in animals by the injection of homogenized brain or spinal cord in Freund's adjuvant. "In experimental autoimmune encephalomyelitis, which is a T cell mediated inflammatory model, Sdc-1 deficient mice showed enhanced disease severity compared to WT mice, with increased Th1 and Th17 infiltration in the brain." (PMID 32701966, 2020). "In murine experimental autoimmune encephalomyelitis, Sdc1-/- mice had increased infiltration by disease-causing Th1 and Th17 cells in brain tissue and increased disease severity." (PMID 25184228, 2014).
fetal growth restriction (5 papers, 2015 to 2025). A fetus that does not grow beyond the 10th percentile of conventionally accepted weight for gestational age. "Dysregulations in the expression of proteoglycans such as SDC1 have been associated with fetal growth restriction and PE based on transcriptome data and also serve as a prognostic marker for unfavorable pregnancy outcomes." (PMID 40038668, 2025). "In human, the uteroplacental localization of Syndecan-1 and its reduced expression in pregnancy-associated pathologies, such as the intrauterine growth restriction, suggests an influence of Syndecan-1 in embryo-maternal interactions." (PMID 30825879, 2019). "We also analyzed transcriptomic data of the placenta from various obstetrical syndromes and identified SDC1, among other dysregulated proteoglycan genes, in pre-eclampsia and fetal growth restriction." (PMID 35628608, 2022). "Indeed, altered placental expression of proteoglycans (e.g., syndecan-1; endocan, glypican-3) was reported in obstetrical syndromes, such as pre-eclampsia, fetal growth restriction, and gestational diabetes mellitus, pointing to their potential roles in the development of these syndromes." (PMID 35628608, 2022).
HELLP syndrome (5 papers, 2016 to 2023). A life-threatening condition that can potentially complicate pregnancy. "Soluble syndecan-1 among normotensive pregnant women (551 ng/ml, IQR: 307–920), preeclamptic women with HELLP syndrome (644 ng/ml, IQR: 286–919 ng/ml) and preeclamptic women without HELLP (447 ng/ml, IQR: 267–734 ng/ml) are similar." (PMID 33623064, 2021). "When complicated with HELLP syndrome, however, the STB apical surface showed strong Sdc1 positivity." (PMID 27299886, 2016).
Hyperglycemia (5 papers, 2013 to 2024). An increased concentration of glucose in the blood. "The involvement of SDC1 in hyperglycaemia‐induced EndMT within glomerular endothelial cells remains unexplored." (PMID 38686489, 2024). "All above indicated a progressive role of hyperglycaemia in EndMT by inhibiting SDC1 expression, thus participating in the occurrence of metabolic memory and DKD." (PMID 38686489, 2024). "This study demonstrated that the hyperglycaemia‐mediated interaction between Sirt7 and HIC1 exerts a role in the metabolic memory in DKD by inactivating SDC1 transcription and mediating EndMT despite glucose normalization in HGECs." (PMID 38686489, 2024). "Our data indicated a downregulation of hyperglycaemia‐induced αSMA by Sirt7 overexpression supplemented with glucose normalization, which increased the hyperglycaemia‐mediated reduction of HIC1, SDC1 and CD31 expression in the kidneys of the rats, while insulin alone did not work." (PMID 38686489, 2024). "Therefore, we developed diabetic mice/cell models, applied biological experiments to study the alterations of Sdc1 and HPSE in high-glucose/hyperglycaemia (HG) conditions, and then investigated the subsequent changes of barrier function of intestinal epithelium and the possible regulation mechanism." (PMID 25702768, 2015). "Syndecan-1 (Sdc1) and its endo-beta-d-glucuronidase heparanase (HPSE) are implicated in maintenance of intestinal epithelial barrier (IEB), but their alterations and roles in high-glucose/hyperglycaemia (HG) conditions have not been fully investigated." (PMID 25702768, 2015).
hypertriglyceridemia (5 papers, 2010 to 2023). A laboratory test result indicating elevated triglyceride concentration in the blood. "Specifically, loss of hepatic SDC1 results in mice with impaired very-low-density lipoprotein metabolism and hypertriglyceridemia." (PMID 31752080, 2019). "Hence, reduced SDC1 expression or increased shedding contributes to the associated hypertriglyceridemia in T2D patients." (PMID 32508807, 2020). "In addition, intensive shedding of Sdc1 from the surface of hepatocytes may cause hypertriglyceridemia." (PMID 29151984, 2017). "Note that mutants lacking the transmembrane heparan sulfate proteoglycan, syndecan 1, or hepatocyte sulfotransferases involved in heparan sulfate assembly develop hypertriglyceridemia due to defects in hepatic clearance of remnant particles." (PMID 21085708, 2010). "Further research is required to determine whether or not a compensatory increase in hepatic Sdc1 expression can prevent the hypertriglyceridemia in ApoE-/- mice." (PMID 29151984, 2017).
lung adenocarcinoma (5 papers, 2009 to 2025). A carcinoma that arises from the lung and is characterized by the presence of malignant glandular epithelial cells. "Here, we report that loss of nuclear SDC1 is associated with cellular elongation and an E-cadherin-to-N-cadherin switch during TGF-β1-induced EMT in human A549 lung adenocarcinoma cells." (PMID 34208075, 2021). "Further, among all lung adenocarcinoma patients analyzed, three patients expressed high levels (upper 20%) of all three critical genes SCGB3A2, SDC1, and CASP4, and all of them survived up to 40 months, although the “n” number is too small to establish significance." (PMID 33452234, 2021).
lupus nephritis (5 papers, 2021 to 2026). Glomerulonephritis in the context of systemic lupus erythematosus. "In a molecular signature study for antibody-secreting cells (ASC) in lupus nephritis published in 2021, a Syndecan-1 positive cell in the renal interstitium was defined as an ASC." (PMID 36834923, 2023). "There were several studies involving Syndecan-1 in lupus nephritis." (PMID 36834923, 2023). "The tubular epithelia expressed much less Syndecan-1 in these 3 lupus nephritis patients." (PMID 36834923, 2023). "Most studies checked the availability of serum Syndecan-1 levels as a marker for lupus nephritis." (PMID 36834923, 2023). "Comparison of syndecan-1, hyaluronan, thrombomodulin and VCAM-1 as putative biomarkers for lupus nephritis compared to conventional serological and clinical markers of disease." (PMID 37854589, 2023).
prostate tumors (5 papers, 2013 to 2024). "Up-regulation of SDC-1 is associated with more aggressive prostate tumors." (PMID 38396744, 2024). "Gene expression analysis from RNA sequencing data of two GEMM of PCa showed several essential changes in Sdc1–4 in prostate tumors at different stages of tumor progression." (PMID 34445387, 2021). "In prostate tumor tissues, a marked attenuation of total decorin and lumican expression was evident, whereas syndecan-1 and glypican-1 expression was increased in tumor stroma and attenuated in tumor epithelial cells." (PMID 32847060, 2020). "We have previously shown syndecan-1 to be important for the tumorigenicity and serial reproducibility of prostatic tumor-initiating cells, as well as for forming tumorigenic microspheres." (PMID 26514209, 2015). "Additionally, an aggrecan, syndecan-1, and glypican-1 expressions were detected in some prostate tumours." (PMID 23691363, 2013). "As a result, expression patterns for main proteoglycans in prostate tumours were highly individual with an ubiquitous expression for versican and tendency for the decreased decorin and lumican expressions and increased syndecan-1 and glypican-1 expressions in tumour tissues." (PMID 23691363, 2013). "In prostate tumours, complex changes in proteoglycans occur, with a common trend towards decrease of decorin and lumican expressions, and increase an overall expression of syndecan-1 and glypican-1, shifted from the epithelial cells to tumour stroma." (PMID 23691363, 2013). "A similar effect was shown for the syndecan-1 expression change in prostate tumours." (PMID 23691363, 2013). "However, most of the results on the increased expression of syndecan-1 in prostate tumours were shown by immunohistochemistry." (PMID 23691363, 2013). "In this study, expression of cell surface and stromal proteoglycans (glypican-1, perlecan, syndecan-1, aggrecan, versican, NG2, brevican, decorin, and lumican) in normal tissue and prostate tumours was determined by RT-PCR analysis and immunostaining with core protein- and GAG-specific antibodies." (PMID 23691363, 2013).